HNF1A (HNF1 homeobox A)
Diseases named in the same sentence as HNF1A in open-access papers (continued):
Sharing a sentence is not in itself a finding about the gene and the disease.
coronary artery disease (18 papers, 2010 to 2025). "In our study, we found four genes with single nucleotide variants (SNVs) associated with coronary artery disease—HNF1A, LOX, SMAD3, and SMARCA4, and one gene, EBF1, with a SNV associated with carotid intima media thickness for the gens in significant modules." (PMID 35925965, 2022). "Recently, polymorphisms in the gene for HNF1α have been linked to the levels of C-reactive protein and coronary artery disease." (PMID 21062467, 2010). "We investigated the association of the rs2259816 polymorphism in the HNF1A gene with the circulating level of C-reactive protein and the hazard of coronary artery disease in the LURIC Study cohort." (PMID 21062467, 2010). "Furthermore, a genetic variant in HNF1A was involved in a genetic score that is able to identify individuals at high risk of coronary heart disease, and with the largest relative and absolute clinical benefit with statin therapy, which is widely used for decreasing cholesterol levels." (PMID 35109885, 2022). "We examined the role of hepatic nuclear factor-1 alpha (HNF1a) gene polymorphism on coronary artery disease (CAD) traits in 4631 Saudi angiographed individuals (2419 CAD versus 2212 controls) using TaqMan assay on ABI Prism 7900HT sequence detection system." (PMID 25057215, 2014). "For instance, a positive local genetic correlation was observed between MI and HDL cholesterol on chromosome 12, a region enriched with genes implicated in lipid metabolism, including HNF1A, which is known to affect HDL levels and coronary artery disease risk." (PMID 40630117, 2025). "The most common variants in HNF1A are rs1169288 (A/C, Ile27Leu), rs2464196 (G/A, Ser487Asn), and rs1169310 (C/T), which have been reported to be associated with the CRP level, coronary artery disease, and diabetic retinopathy." (PMID 31915469, 2019). "Recently, polymorphisms in the HNF1A gene (also known asTCF1, MIM 142410) have been linked to the levels of C-reactive protein and coronary artery disease." (PMID 21062467, 2010). "Furthermore, the G-allele of the SNP rs1183910 in the HNF1A locus increases serum CRP levels and is associated with a lower risk of coronary artery disease." (PMID 25768928, 2015). "The gene has similarly been implicated in coronary artery disease (CAD)/myocardial infarction (MI) as well as its risk traits, including dyslipidemic disorders, whereby an increased risk for CAD was also observed in T2DM patients harbouring HNF1a mutations." (PMID 25057215, 2014). "Recently, HNF1α single nucleotide polymorphisms (SNPs) have been associated with plasma C-reactive protein (CRP), LDL cholesterol and gamma glutamyltransferase (GGT), and coronary heart disease." (PMID 21203500, 2010). "In the LURIC Study cohort the A-allele of the rs2259816 polymorphism in the HNF1A gene is associated with decreased CRP but not with coronary artery disease." (PMID 21062467, 2010). "Currently, HNF1A gene variants are associated with maturity onset diabetes of the young (MODY), C-reactive protein (CRP) levels, gamma-glutamyl transferase (GGT) levels, total cholesterol (TC) levels, pancreatic cancer, coronary artery disease, and metabolic syndrome (MS)." (PMID 31915469, 2019). "The possible function(s) of HNF1α are a focus of intense current interest following its recently reported associations in GWAS with plasma C-reactive protein (CRP), gamma-glutamyl transferase (GGT), LDL cholesterol and apolipoprotein and coronary artery disease." (PMID 21203500, 2010).
metabolic syndrome (18 papers, 2009 to 2025). A cluster of metabolic risk factors for CARDIOVASCULAR DISEASES and TYPE 2 DIABETES MELLITUS. "The findings of an association with dyslipidemia are in agreement with previous studies implicating some of the HNF1a gene variants in dyslipidemia, T2DM, hTG, and high low-density lipoprotein-cholesterol (hLDLC) levels." (PMID 25057215, 2014). "In this study, we aimed to assess the association of HNF1A gene and haplotypes with the metabolic syndrome (MetS) and its components through an association study in the Tunisian population as well as by a meta-analysis." (PMID 35109885, 2022). "Clinically, HNF-1α (MODY3) and HNF-1β (MODY5) mutations are closely associated with dyslipidemia, proteinuria, and CKD progression, with lipotoxicity serving as a key pathogenic driver." (PMID 41291157, 2025). "Meta-analyses of the European ancestry genome-wide association study (GWAS) suggested that variants of rs3846663 in HMGCR, rs1501908 between TIMD4 and HAVCR1, rs2650000 near HNF1A, and rs6102059 near MAFB were associated with dyslipidemia." (PMID 37334397, 2023). "The mechanism through which BBR acts to correct dyslipidemia works through the degradation and ubiquitination of hepatocyte nuclear factor 1 alpha (HNF-1α), resulting in an inhibitor of PCSK9." (PMID 37346213, 2023). "In contrast, HNF1A-MODY was aggravated in the brother by classical insulin resistant type 2 diabetes or features of metabolic syndrome indicated by dyslipidemia with severe hypertriglyceridemia and hepatic steatosis." (PMID 27142837, 2016). "Three missense variants of metabolic syndrome-related genes, namely, rs671 in ALDH2, rs1169288 in HNF1A and rs1260326 in GCKR, significantly associate with AAT levels (P≤1.5 × 10−12)." (PMID 26174136, 2015). "Put together, our findings furnish unequivocal support to the notion that the chromosomal region encompassing the HNF1a gene is a susceptibility locus for MI, HTN, T2DM, and dyslipidemia, the important causes for atherosclerosis." (PMID 25057215, 2014). "Our results suggest that the HNF1a is a common susceptibility gene for MI, T2DM, hypertension, and dyslipidemia." (PMID 25057215, 2014). "While the role of HNF1α has been observed in hypertension, dyslipidemia, and genetic variations, it remains unclear whether HNF1α rs1169288 SNP is involved in metabolic syndrome, cardiovascular disease, and stroke." (PMID 41379817, 2025). "We conclude that the HNF1a locus constitutes a risk factor for MI, T2DM HTN, and dyslipidemia." (PMID 25057215, 2014). "In the Women’s Genome Health Study, metabolic-syndrome related genes, such as LEPR, HNF1A, IL6R, and GCKR, were correlated to CRP expression and inflammation." (PMID 35845045, 2022). "Statins induce PCSK9 gene expression via hepatocyte nuclear factor 1 alpha (HNF1a) and reduce LDL cholesterol in dyslipidemia hamsters." (PMID 31114503, 2019). "Although the term photoreceptor outer segment has no biological relevance to CRP or inflammation, the genes enriched in this pathway have biological relevance to CRP (HNF1A), high triglycerides (PCDH15) and metabolic syndrome (GNAT3)." (PMID 24763700, 2014). "In keeping with the absence of the metabolic syndrome features, soluble CD36 levels are significantly lower in the HNF1A-MODY participants when compared to the normoglycaemic HNF1A-MODY negative family control group and the T2DM group." (PMID 24069322, 2013).
Obesity (17 papers, 2008 to 2025). Accumulation of substantial excess body fat. "Improvements in obesity-related metabolic abnormalities with the DASH diet have been demonstrated in adolescent populations, and may have synergistic therapeutic effects with specific diabetes subtypes associated with obesity, such as HNF1A-MODY." (PMID 41229546, 2025). "Notably, we made the novel finding that T2D risk, as conferred by HNF1A, GCK, and SLC30A8 genetic variants, may also be modified in the presence/absence of obesity." (PMID 18498634, 2008).
maturity-onset diabetes of the young type 3 (16 papers, 2011 to 2025). Monogenic diabetes caused by inactivating mutation(s) in the gene HNF1A, encoding hepatocyte nuclear factor 1-alpha. "MODY type 3 (MODY 3) is caused by heterozygous mutations in the hepatocyte nuclear factor 1-α (HNF1A) gene and is sensitive to treatment with sulfonylureas." (PMID 39055415, 2024). "In humans, patients carrying mono-allelic mutations in HNF1A suffer from type 3 MODY with renal dysfunctions." (PMID 25793983, 2015). "The most frequent form is HNF-1α-MODY (MODY type 3), which is caused by mutations in the HNF1A gene encoding hepatic nuclear factor 1α." (PMID 22389783, 2011). "While the HNF1A G319S polymorphism demonstrated reduced in vitro capacity to transactivate insulin response, this disorder was not as severe as that seen in some nonsense mutations in HNF1A that underlie MODY type 3." (PMID 21208426, 2011). "In humans HNF1A deficiency is the genetic cause Maturity-Onset Diabetes of the Young type 3 (MODY3)." (PMID 26872257, 2016). "MODY type 3 (MODY 3) is one of those and is caused by heterozygous mutations in the hepatocyte nuclear factor 1-α (HNF1A) gene." (PMID 39055415, 2024). "Although genetic variants in the gene hepatocyte nuclear factor 1-alpha (HNF1A) are associated with Hcy, we chose not to include it in the genetic IV, because of its function in the regulating expression of several liver and pancreatic-islet specific genes and its association with MODY type 3." (PMID 26664883, 2015).
cervical carcinoma (13 papers, 2012 to 2025). A carcinoma arising from either the exocervical squamous epithelium or the endocervical glandular epithelium. "HNF1A overexpression significantly enhances the radiation resistance of cervical cancer cells both in vitro and in vivo." (PMID 40072068, 2025). "HNF1A plays a key role in tumorigenesis and tumor development and is highly expressed in cervical cancer patients, which can promote tumor cell proliferation and shorten the survival period of cervical cancer patients." (PMID 38443412, 2024). "After treating cervical cancer cells with different concentrations of the drug, HNF1A, the main marker gene of cervical cancer, was significantly down-regulated with the increase of drug concentration." (PMID 38443412, 2024). "The results showed that the paclitaxel-loaded metal gel inhibited the proliferation of cervical cancer cells by targeting and suppressing the expression of HNF1A." (PMID 38443412, 2024). "YTHDF3 accelerates the translation of the DNA repair protein RAD51 homologue 4 (RAD51D) in an m6A-dependent manner, thereby mediating effect of hepatocyte nuclear factor 1-alpha (HNF1α) on radioresistance of cervical cancer." (PMID 37714846, 2023). "HNF1α is significantly up-regulated in radioresistant cervical cancer, thus promoting the resistance of cervical cancer cells to radiation." (PMID 37714846, 2023). "HNF1A had been reported to be associated with tumor cell invasion, and inhibition of HNF1A reduced the invasion ability of cervical cancer cells 11, while increasing HNF1A improves liver metastasis of colorectal cancer." (PMID 34234870, 2021). "Earlier it has been demonstrated that tumor suppressor miR-484 modulates the ZEB1 and SMAD222 and WNT/ MAPK pathway by directly targeting HNF1α in cervical cancer cells." (PMID 33214606, 2020). "The results further demonstrated that MMP14 and HNF1A were upregulated in cervical cancer tissues compared with the normal cervix." (PMID 31810492, 2019). "HNF1α expression is significantly upregulated in radioresistant cervical cancer cells." (PMID 38651153, 2024). "Paclitaxel-loaded metal gel may have inhibited the development of cervical cancer through down-regulation of HNF1A, and it is expected to be developed as a novel drug for the treatment of cervical cancer." (PMID 38443412, 2024). "Hnf1α, which is a crucial member of the hepatocyte nuclear factor 1 (HNF1) transcription factor family, functions as a proto-oncogene in cervical cancer and actively participates in the proliferation and EMT of cervical cancer cells." (PMID 38651153, 2024). "At the same time, silencing miR-484 can be down HNF1A/MMP14 and inhibited the growth and metastasis of tumor cells, on the other hand, the overexpression of HNF1A/MMP14 promoted the adhesion and EMT process in cervical cancer." (PMID 34234870, 2021). "Collectively, the present work provides the first evidence of the coordination of methylation modulated miR-484 and MMP14/HNF1A in the regulation of the cell adhesion, EMT, and the β1-integrin pathway during cervical cancer carcinogenesis." (PMID 31810492, 2019). "For instance, silencing of miR-484 could aggravate the malignancy of cervical cancer cells by inhibiting MMP14 and HNF1A." (PMID 32232409, 2020). "To further explore the expression levels of MMP14 and HNF1A in cervical cancer, we performed RT-qPCR analyses to examine their expression levels in 20 pairs of CC tissues and adjacent non-tumor tissues as well as a panel of cervical cancer cell lines." (PMID 31810492, 2019).
steatosis (13 papers, 2011 to 2025). Increased lipid within the cytoplasm of cells. "HNF-1α inactivated HCA is associated with extensive steatosis and a diffuse and homogenous signal dropout on T1 weighted images." (PMID 41321651, 2025). "HNF1α-mutated HCA (H-HCA) are characterized by a marked steatosis and show activation of glycolysis, lipogenesis, translational machinery and mTOR pathway." (PMID 21975049, 2011). "Steatosis within nodule is variable and less extensive compared with HNF-1α-mutated HCAs." (PMID 23606972, 2013). "HNF1α-mutated HCA (H-HCA) are phenotypically characterized by a marked steatosis." (PMID 21975049, 2011). "Indeed, HNF-1α-mutated HCA is characterized by diffuse intralesional steatosis." (PMID 23606972, 2013). "A marked steatosis of inactivated HNF-1α HAs was in fact substituted by an enriched vascularity and an apparently more aggressive phenotype in the ARID1A-mutated HA, which is consistent with reports of malignant transformation of HNF1A-related HAs." (PMID 39408812, 2024). "Adding NSC74859 after the downregulation of HNF1α expression reversed the increase in the number of red granular lipid droplets in LO2 cells induced by FFA downregulation of HNF1α expression, aggravating the phenomenon of steatosis in LO2 cells." (PMID 31223625, 2019). "Inactivating mutations in the HNF1A (TCF1) gene causing loss of hepatocyte nuclear factor 1α (HNF-1α) expression define H-HCA, which are characterized histologically by marked steatosis and bland hepatocyte cytology." (PMID 26961851, 2016). "This is of particular interest as H-HCAs and HNF1α-KO mouse livers are characterized by steatosis." (PMID 32784704, 2020). "Our results showed that FFA-induced hepatocyte LO2 steatosis inhibited the expression of HNF1α." (PMID 31223625, 2019). "Downregulation of HNF1α expression aggravated FFA-induced steatosis of LO2 hepatocytes." (PMID 31223625, 2019). "In this study, FFA-induced steatosis LO2 hepatocytes were used as an in vitro model to evaluate both the regulation of HNF1α on hepatic lipid metabolism and the relationship between the HNF1α and SOCS3-STAT3 signaling pathways." (PMID 31223625, 2019). "The results of Oil Red O staining showed that after upregulating the expression of HNF1α, the number of red granular lipid droplets in LFA-induced LO2 cells decreased and steatosis was reduced when compared to the control." (PMID 31223625, 2019). "Dual-luciferase reporter assays confirmed the transcriptional activation between RelA and HNF1α, highlighting the lack of reciprocal transcriptional activation between these factors in hepatocyte steatosis." (PMID 39910053, 2025). "To understand the mechanism underlying the protective effects of fucoidan against ethanol-induced liver injury and steatosis, we analyzed the hepatic expression of p-AMPKα, SIRT1, ChREBP, PGC-1α, and HNF-1α, which regulate hepatic fat metabolism and inflammatory response." (PMID 33994911, 2021). "An HCA with important amount of steatosis noticed on chemical shift images does not always belong to the HNF1α group." (PMID 22811588, 2012). "Five lesions displayed important steatosis (>50%) without belonging to the HNF1α group." (PMID 22811588, 2012).
hyperinsulinism (12 papers, 2010 to 2026). Abnormally high levels of insulin in the blood. "Furthermore, novel case reports have identified HNF1A mutations presenting with complex phenotypes, including congenital hyperinsulinism accompanied by hepatomegaly and renal tubular dysfunction, suggesting that HNF1A-related disease can also be syndromic in nature." (PMID 41614934, 2026). "Recently, mutations in the transcription factor, hepatocyte nuclear factor 1-alpha (HNF-1α), encoded by HNF1A and known to cause MODY3, have been shown to also present with hyperinsulinism in infancy." (PMID 23384201, 2013). "The fetal insulin hypothesis would predict that affected individuals have a low birthweight, yet individuals with HNF1A-MODY have normal birthweights and inheritance of HNF4A-MODY is associated with fetal and neonatal hyperinsulinism and macrosomia." (PMID 33569631, 2021). "An exception to this notion is that HNF4A mutations cause transient in utero and neonatal hyperinsulinism, which later evolves to decreased insulin secretion, whereas HNF1A mutations develop the latter phenotype without early hyperinsulinism." (PMID 20523905, 2010). "Among the reported Turkish patients, there was no case with exercise-induced hyperinsulinism (SLC16A1), glucokinase-induced hyperinsulinism, or mutations in the UCP2, HNF4A, and HNF1A genes, while one patient had GLUD1 gene mutation." (PMID 27181376, 2016).
Hypoglycemia (12 papers, 2013 to 2025). A decreased concentration of glucose in the blood. "In the case of HNF1A, the risk of hypoglycemia must be considered, as insulin sensitivity can be normal or increased in individuals with HNF1A‐MODY." (PMID 39511990, 2024). "To investigate effects of HNF1A loss on glucagon secretion during hypoglycemia, we performed i.p. insulin tolerance tests (IP-ITT)." (PMID 37943614, 2023). "Because of the drug history and hypoglycemia symptoms of the proband’s father, they were suspected to have HNF-1A or HNF-4A mutation." (PMID 28105082, 2017).
colon cancer (11 papers, 2010 to 2025). "Flag-tagged HNF1A and HNF1AA98V variant expression vectors were transfected into the HCT116 colon cancer cell line, which expresses minimal endogenous HNF1A protein." (PMID 37219942, 2023). "In agreement with the presence of CpG islands in the HNF1A promoter, treatments of UGT1A1-negative HCT116 colon cancer cells with a DNA methyltransferase inhibitor restore HNF1A gene expression, as observed for UGT1A1." (PMID 20096102, 2010). "We found that the colon cancer cell lines HCT-116 and HCT-15 exhibited a confluence-dependent increase in CD26 mRNA and protein, associated with decreased expression of c-Myc, increased USF-1 and Cdx 2 levels, and unchanged HNF-1α expression." (PMID 21284881, 2011). "In contrast, aberrant hypermethylation of HNF1A downregulates the expression of UDP-glucuronosyltransferase 1A1 (UGT1A1), which remodels drug metabolism and transport pathways, locally inactivating anticancer drugs by glucuronidation in colon cancer cells." (PMID 37889117, 2023).